MMP2 (matrix metallopeptidase 2)
Diseases named in the same sentence as MMP2 in open-access papers (continued):
Sharing a sentence is not in itself a finding about the gene and the disease.
pancreatic cancer (continued). "Furthermore, we show that Nodal promotes pancreatic cancer cell migration and invasion, induces epithelial-mesenchymal transition (EMT) and enhances the expression of matrix metalloproteinase-2 (MMP2) and CXC chemokine receptor 4 (CXCR4)." (PMID 25557170, 2015). "Moreover, some researches were reported that high expression of MMP-2 and MMP-9 was found in pancreatic cancer." (PMID 25496480, 2014). "MMPs are believed to be important facilitators of cancer cell invasion in past studies by resolving basement membrane proteins, Because of rich MMP-2 production found in the stromal cells of pancreatic cancer and the expression of MMP-9 increasing in adjacent pancreatic cancer cells." (PMID 25496480, 2014). "The knockdown of OCT4 inhibited the proliferation and invasion of pancreatic cancer cells (Panc-1) expressing high levels of OCT4, accompanied with decreased expression of AKT, proliferating cell nuclear antigen (PCNA) and matrix metalloproteinase-2 (MMP-2)." (PMID 25017645, 2014). "MMP-2 rather than MMP-9 was activated in the metastatic pancreatic cancer, and it is secreted as an inactive zymogen and requires distinct activation processes." (PMID 25170871, 2014). "In this study, based on the present findings, we inferred that HCS could inhibit the progression of advanced pancreatic cancer with liver metastasis through down-regulating the expression of VEGF, MMP-2 and MMP-9." (PMID 25496480, 2014). "Among them, MMP-2 and MMP-9 are highly expressed in pancreatic cancer." (PMID 24505326, 2014). "Furthermore, PSCs derived Galectin-1 promotes the proliferative activity, MMP2 and MMP9 expression and invasion of pancreatic cancer cells in vitro, and tumor establishment and growth in vivo." (PMID 24595374, 2014). "In fact, MMP-2 was upregulated in several human pancreatic cancer cell lines and SHh overexpression in PAAD cells activated the Hedgehog signaling pathway in stromal pancreatic stellate cells rather than activating PAAD cells directly to augment the output of MMP-2 as well as MMP-9." (PMID 35338115, 2022). "To test this prediction, we analyzed the proteases found in both stromal and tumor cells with a focus on the soluble MMP2 and MMP9 proteases and the transmembrane MT1-MMP proteases that are known to drive matrix degradation in many tumor types, including breast, prostate, and pancreatic cancer." (PMID 33740019, 2021). "For example, M2-like TAMs can increase MMP2 and MMP9 activity in pancreatic cancer cells and decrease E-cadherin, indicating that EMT and Toll-like receptor (TLR) 4 expression and IL-10 production, are upregulated in M2-like TAMs to stimulate EMT when cocultured with pancreatic cancer cells." (PMID 30060755, 2018). "We also detected that the protein levels of MMP2 and MMP9 were downregulated by miR-675-5p mimics in Patu8988 cells whereas miR-675-5p inhibitors upregulated MMP2 and MMP9 in SW1990 cells, suggesting that miR-675-5p can suppress the migration and invasion of pancreatic cancer." (PMID 28212565, 2017). "Also, LIN28A overexpression resulted in upregulation of MMP2 and MMP9, while LIN28A knockdown downregulated the expression of MMP2 and MMP9 in PANC1 cells, indicating that LIN28A might be critical for invasion of pancreatic cancer cells." (PMID 26910839, 2016). "Previous observations show that upregulation of E-cadherin and a concomitant reduction in MMP-2/MMP-9 levels might negatively regulate cell proliferation, invasiveness, and adhesion of K1 papillary thyroid cancer cells and pancreatic cancer cell lines MIAPaCa-2 and BxPC-3." (PMID 24581171, 2014). "In vitro and in vivo experiments indicated that TGF-β1 upregulated Galectin-1 expression in PSCs, which could further promotes the proliferative activity, MMP2 and MMP9 expression, and invasion of pancreatic cancer cells, as well as the tumor establishment and growth." (PMID 24595374, 2014).
pancreatic cancer (continued). "Finally, a study focusing on pancreatic cancer demonstrated that, L1CAM-ECD cleaved from Schwann cells homotypically interacts with L1CAM on tumor cells leading to the activation of ERK and STAT3-mediated expression of MMP-2 and -9 which facilitates cancerous nerve invasion." (PMID 31455004, 2019). "Consequently, the induction of MMP‐2 by insulin may contribute to the degradation of ECM, the breakdown of the basement membrane, increased local infiltration and distant metastasis, which may explain the increased incidence of pancreatic cancer in patients with hyperinsulinemia and type 2 diabetes." (PMID 30838710, 2019). "Notably, western blot analysis indicated upregulation of MMP2 expression in GnRH-inhibited Panc1 cells, whereas the regulation of MMP9 expression was not obvious, suggesting that MMP2 might play a role in GnRH-related invasion and migration in pancreatic cancer cells." (PMID 31263453, 2019). "Pancreatic carcinoma patients with lymph node involvement and advanced TNM stage exhibit a higher MMP-2 level than patients without." (PMID 29949618, 2018). "In the present study, we compared the expression levels of MMP-2, MMP-7, MMP-9 and MMP-13 in pancreatic cancer cells with and without leptin treatment." (PMID 25948792, 2015). "We speculated that TNC might regulate MMP9 expression and thus be involved in metastatic processes in pancreatic cancer, but we found that the expression of TNC did not affect MMP2 expression in these cells." (PMID 29088796, 2017).
liver fibrosis (196 papers, 2008 to 2026). "An increase in MMP-2 causes membrane damage in the space of Disse, which activates HSCs and advances liver fibrosis." (PMID 38111317, 2024). "Hepatic fibrosis is caused by interstitial collagen replacement, which is promoted by increased MMP-2 activity, which is also linked to higher disruption of normal hepatic architecture." (PMID 36985782, 2023). "It should also be noted that previous studies have reported contradictory findings on the association of serum MMP-2 and liver fibrosis." (PMID 36551935, 2022). "MMP‐12 expression has been linked to hepatic fibrosis through the attenuation of IL‐13‐dependent induction of MMP‐2, −9, and −13 in liver." (PMID 32951289, 2020). "COL1α2 and COL5α2 are common ECM components in fibrotic livers, whereas MMP2 is a collagenase that is increased during liver fibrosis and associated with disease progression." (PMID 30670377, 2019). "Luteolin administration is known to reduce liver fibrosis associated MMP-2 and MMP-9 induced by Pentylentetrazol toxicity." (PMID 31170991, 2019). "MMP-2 secreted from hepatic stellate cells in liver disease has high diagnostic accuracy of 92% to detect liver fibrosis." (PMID 29255622, 2018). "Decreased gelatinase activity, particularly MMP-2, is associated with increased liver fibrosis development." (PMID 27672655, 2016). "Further study is important to investigate the mechanism underling the regulation of the expression and activity of MMP-2 in liver fibrosis." (PMID 21731450, 2011). "MMP2-deficient mice present with liver fibrosis with increased Collagen type I protein levels." (PMID 34608249, 2021). "We also investigated the levels of α1 type 1 collagen (Col1α1), a factor associated with collagen fiber degradation, liver fibrosis‐related genes such as matrix metallopeptidase‐2 (MMP‐2) and tissue inhibitor of metalloproteinase‐1 (TIMP1), an inhibitor of MMP." (PMID 34532001, 2021). "Increased hepatic MMP-2 levels have been associated with liver fibrosis." (PMID 33799469, 2021). "However, recent studies have reported that MMP-2-deficient animals show increased liver fibrosis, due to increased collagen I synthesis and suppressed TIMP-1 upregulation." (PMID 23056273, 2012). "Importantly, it was suggested that serum MMP2 levels could serve as a diagnostic marker to assess the level of liver fibrosis in patients with NASH." (PMID 34745017, 2021). "For instance, Colchicine increases the degree of fibrosis in rats with liver fibrosis by reducing MMP-2 expression, which relates to Colchicine’s role in inhibiting MMP-2 expression as part of its anti-fibrotic effects." (PMID 40283497, 2025). "In contrast, aged mice exhibited hepatic fibrosis, with increased collagen deposition and upregulation of genes related to fibrosis (Acta2, MMP2, TGF-ß1, and Col1a2), cirrhosis (CXCR4, SOX9, DCN, and MFAP4), and cancer (Bcl2, CDKN2a, c-Myc, and Fn1)." (PMID 39851554, 2025). "The activation of the TGF-β/SMAD signaling pathway in HSCs resulted in the upregulation of several key genes associated with hepatic fibrosis, including TIMP1, SMAD2, SMAD3, COL1A1, and MMP2, as well as increased secretion of MMP-9 protein." (PMID 39201682, 2024). "MMP2 is reported to be responsible for the cleavage of fibronectin into fragments and for the progression of liver fibrosis." (PMID 38545255, 2024). "Apart from collagenases and gelatinases, MMP-2 and -9 have been shown to be a potential target for the treatment of liver fibrosis." (PMID 37808009, 2023). "The consumption of gallic acid regulated hepatic fibrosis by regulating the mRNA levels of MMP-2 and tissue inhibitor of MMP-1 in carbon tetrachloride-induced liver injury mice." (PMID 37760047, 2023). "The possible mechanism of ALHX for the inhibition of hepatic fibrosis is related to enhancing MMP2 activity in liver tissue and promoting extracellular matrix degradation by hepatoprotective enzymes." (PMID 37025490, 2023).
liver fibrosis (continued). "The reduction of hepatic inflammation correlated with a reduction in liver fibrosis and an increase in gelatinase MMPs (MMP-2 and MMP-9)." (PMID 37242695, 2023). "It has been demonstrated that it reduces the expression of NF-k light chain enhancer of activated B cells, which inhibits MMP-2 activity in CCl4-induced hepatic fibrosis." (PMID 36985782, 2023). "Gene expression of Col1a1, TGFβ-1, TIMP-1, MMP-2, and MMP-9, which are associated with liver fibrosis, was significantly higher in MCDHFD mice than in control animals." (PMID 37107346, 2023). "In CCl4-induced liver fibrosis, mRNA expression of MMP2 and MMP9 in the liver is elevated significantly." (PMID 37266145, 2023). "It caused a reduction in collagen levels, MMP-2, TIMP-2, and HSC activation and inhibited hepatic fibrosis in the CCl4 liver fibrosis rat model." (PMID 36985782, 2023). "On the other hand, a study in mice with induced liver fibrosis reported increased MMP2 mRNA and decreased MMP9 mRNA." (PMID 36032279, 2022). "Several studies have shown that MMP2 and MMP9 are associated with liver fibrosis and that trans-THSG impeded fibrosis-associated extracellular matrix remodeling by inhibiting the transcription of MMP2 and MMP9." (PMID 35845925, 2022). "We also analyzed circulating levels of MMP-2, which is known to degrade the components of the extracellular matrix and to be involved in tissue remodeling and in the development of liver fibrosis during HCV infection." (PMID 36233234, 2022). "As a result, the levels of α-SMA, TGF-β1 and MMP-2 were down-regulated for the further treatment of liver fibrosis." (PMID 36145508, 2022). "Of note, we found that at MH stage, loss of FOXA2 led to a significant increase in the expression of mRNA levels of genes associated with hepatic fibrosis and HSC activation, such as PDGF, MMP2, TGFβ2, TGFβ3, TGFβR2, and DLK1 among others." (PMID 35973994, 2022). "While both gelatinases are upregulated in the context of fibrogenesis, paradoxically hepatic fibrosis was exacerbated in MMP2-KO mice." (PMID 34745017, 2021). "BMP7 treatment alleviated liver fibrosis in mice, with decreased Collagen type I and increased MMP2 expression levels." (PMID 34608249, 2021). "Apart from collagenases, gelatinases MMP-2 and -9 are also exploited as potential targets for the treatment of liver fibrosis." (PMID 32414178, 2020). "MMP2, MMP8, and MMP9 have all been reported to be associated with the progression of liver fibrosis and cirrhosis." (PMID 33315911, 2020). "Previous data have documented the capacity of OCA to modulate MMP-2 expression in hepatic stellate cells promoting resolution of liver fibrosis." (PMID 32911524, 2020). "MMP-2 suppresses collagen I expression, and the loss of MMP-2 aggravates fibrosis, suggesting that MMP-2 suppresses TIMP-1 upregulation during liver fibrosis." (PMID 32664553, 2020). "In contrast to these pro-fibrotic MMPs, animal models suggest that augmented levels of MMP1 decrease fibroplasia in liver, muscle and heart, while MMP2 decreased type I collagen production in experimental liver fibrosis." (PMID 32171287, 2020). "Several studies have shown that MMP2, one of the most studied enzymes in liver fibrosis, is mainly secreted by KCs and by HSCs while MMP-9 (gelatinase B) is predominantly expressed in KCs but can be also expressed by neutrophils, macrophages and fibroblasts." (PMID 32911524, 2020). "MMP-2 is expressed by various liver cells, most abundantly by HSCs and KCs, and is one of the widely studied enzymes in liver fibrosis." (PMID 32414178, 2020). "El-Lakkany reported that silymarin at 750 mg/kg alleviated Schistosoma mansoni-induced liver fibrosis by downregulating MMP-2 and TGF-β1 and upregulating glutathione (GSH)." (PMID 33082829, 2020). "It was reported that the iron overload during hepatic fibrosis is involved on collagen biosynthesis, cell proliferation, and expression of MMP-2 in rat hepatic stellate cells." (PMID 30679730, 2019).
liver fibrosis (continued). "MMP-2 for being an autocrine factor in hepatic stellate cells for proliferation and migration enhances liver fibrosis when overexpressed." (PMID 31653214, 2019). "MMP-2 was reported to predominately influence the degree of collagen deposition and limit HSCs activities after liver injury, thereby inhibit hepatic fibrosis." (PMID 29214887, 2018). "In the late stage, MMPs including MMP-2 are beneficial to the treatment of hepatic fibrosis through degrading ECM." (PMID 28396867, 2017). "MMP2 is important in the formation of hepatic fibrosis, degrading certain kinds of extra cellular matrix (ECM) such as collagens and proteoglycans." (PMID 28335383, 2017). "In liver fibrosis, ghrelin has been found to inhibit extracellular matrix formation by maintaining the balance between matrix metalloproteinases (MMP2) and tissue inhibitor of matrix metalloproteinases (TIMP1)." (PMID 29100513, 2017). "In particular, it was shown that the antioxidative activity of BBR contributes to improvement of experimental hepatic fibrosis via stimulating matrix metalloproteinase-2 (MMP-2)." (PMID 27239214, 2016). "MMP-2 promotes hepatic fibrosis by increasing HSC proliferation and it is required for degradation of the accumulated collagen." (PMID 26537990, 2015). "Treatment with betulin and betulinic acid inhibited expression of TNF-α, TGF-β1, tissue inhibitor of metalloproteinase (TIMP)-1, TIMP-2, and activated matrix metalloproteinase (MMP)-2 in alcohol-induced liver fibrosis in vivo." (PMID 25897319, 2015). "It is well-established that hepatic stellate cells (HSCs) are central mediators of hepatic fibrosis, and matrix metalloproteinase-2 (MMP-2) is important in the formation of liver fibrosis." (PMID 26017616, 2015). "Activated hepatic stellate cells contribute to liver fibrosis via abnormal production of MMP2, TIMP1, and TIMP2 through the secretion of various inflammatory cytokines from Kupffer cells and T cells." (PMID 26358689, 2015). "Measurements of other new potential biomarkers for staging liver fibrosis such as fibulin-5, MMP-2 or TIMP-1 further have the potential to improve the accuracy of non-invasive estimates of liver fibrosis." (PMID 26460565, 2015). "Secondly, we confirmed that astaxanthin (40 mg/kg and 80 mg/kg) effectively increased the expression of MMP2, which participated in the regression of liver fibrosis through cleavage of the fibrillar ECM." (PMID 24860243, 2014). "Although these data are not inconsistent with a role for MMP-2 in influencing collagen expression, they do suggest that other MMP-2-dependent pathways contribute to liver fibrosis." (PMID 24713275, 2014). "Our results showed that astaxanthin ameliorated liver fibrosis partly by preserving the balance between MMP2/TIMP1." (PMID 24860243, 2014). "Serum apoptotic cytokeratine 18 neoepitope M30 (CK-18 M30) and matrix metalloproteinase 2 (MMP-2) have been popular markers for detecting liver fibrosis in recent years." (PMID 24032040, 2013). "Serum apoptotic cytokeratine 18 neoepitope M30 (CK-18 M30) and matrix metalloproteinase 2 (MMP-2) are among the popular noninvasive markers used to detect liver fibrosis." (PMID 24032040, 2013). "Our study indicated that CK-18 M30 and MMP-2 levels were higher in CHB patients compared to healthy controls and they were in association with significant hepatic fibrosis, especially cirrhosis." (PMID 24032040, 2013). "MMP expression is increased in liver fibrosis, and MMP-2 is expressed and secreted by activated HSCs." (PMID 24116114, 2013). "In vivo experiment suggested that at the beginning of liver fibrosis, MMP-2 expression and activity were decreased, and fewer HSCs were activated." (PMID 21731450, 2011). "MMP-2 has been shown to promote the formation and development of liver fibrosis, mainly through the regulation of the activation, proliferation, and migration of HSCs." (PMID 21731450, 2011).